GKN1 (gastrokine 1)
Diseases named in the same sentence as GKN1 in open-access papers (continued):
Sharing a sentence is not in itself a finding about the gene and the disease.
gastric cancer (continued). "However, serum GKN1 concentration discriminated patients with gastric cancer from those with non‐gastric cancers." (PMID 31376239, 2019). "Next, we investigated whether serum GKN1 protein concentration discriminated healthy individuals from patients with non‐gastric cancers including HCC, CRC, NSCLC, BRC, PAC, OVC, and PRC." (PMID 31376239, 2019). "Furthermore, the serum GKN1 concentrations robustly discriminated the patients with gastric cancer from the patients with colorectal, liver, lung, breast, pancreatic, ovary, and prostatic cancers with AUC values greater than 0.94." (PMID 31376239, 2019). "To determine whether serum GKN1 protein concentration can be used as a novel biomarker for early detection of gastric cancer, we measured the serum GKN1 protein concentrations in 500 patients with gastric cancer and 200 healthy controls." (PMID 31376239, 2019). "Although clinical trials for the screening of serum GKN1 protein concentration prior to clinical application are strongly required, the key strength of this study is that serum GKN1 protein can be used as a potential serological marker for early detection of gastric cancer." (PMID 31376239, 2019). "GKN1 down-regulation in gastric cancer tissues was shown to be associated with high levels of H3K9triMe and with the recruitment of SUV39H1 to the GKN1 promoter, suggesting the presence of an epigenetic transcriptional complex that negatively regulates GKN1 expression in gastric tumors." (PMID 28129645, 2017). "We aimed to ascertain if Gastrokine 1 mRNA in the sera of patients with gastric cancer might be an informative biomarker for the disease." (PMID 27452910, 2016). "As replicative senescence is closely linked to shortening of telomeres and the p16/Rb pathway, we hypothesized that GKN1 may induce senescence of gastric cancer cells by regulating telomere length." (PMID 25344918, 2014). "GKN1 may be a potential chemotherapeutic candidate for gastric cancer treatment, which will ultimately achieve the goal of gastric cancer prevention and remission." (PMID 25344918, 2014). "The present study aims to investigate whether gastrokine 1 (GKN1) induces senescence and apoptosis in gastric cancer cells by regulating telomere length and telomerase activity." (PMID 25344918, 2014). "As the critical shortness of telomeres and the inhibition of telomerase activity lead to apoptosis and senescence, we investigated whether GKN1 could induce gastric cancer cells to undergo senescence and apoptosis by regulating telomere length." (PMID 25344918, 2014). "Although it is unclear how GKN1 controls expression and stability of the c-myc protein, these results suggest that GKN1 may inhibit cell growth by suppressing c-myc-induced telomere elongation in gastric cancer cells." (PMID 25344918, 2014). "Finally, five proteins including GRP78, GSTpi, ApoAI, A1AT and GKN-1 were confirmed and further validated as putative markers of gastric cancer." (PMID 24404153, 2014). "Taken together, these findings suggest that GKN1 may affect the telomere length maintenance pathways by inhibiting not only c-myc-induced hTERT expression but also TRF1 inactivation in gastric cancer cells." (PMID 25344918, 2014). "Interestingly, c-myc mRNA expression was positively correlated with hTERT expression, whereas GKN1 expression was inversely correlated with c-myc and hTERT mRNA expression in 35 gastric cancer tissues." (PMID 25344918, 2014). "In addition, our data suggest that the ability of GKN1 to induce apoptosis is an alternative way to eliminate senescent cells in gastric cancer." (PMID 25344918, 2014). "In conclusion, we demonstrated an additional function of the GKN1 gastric tumor suppressor gene, which induces shortening of telomeres by acting as a potential c-myc inhibitor, leading to senescence and apoptosis in gastric cancer cells." (PMID 25344918, 2014).
gastric cancer (continued). "Taken together, these results suggest that GKN1 may shorten telomeres by acting as a potential c-myc inhibitor that eventually leads to senescence and apoptosis in gastric cancer cells." (PMID 25344918, 2014). "In this study, we assessed whether presence of GKN1 could enhance sensitivity of gastric cancer cells to 5-FU treatment." (PMID 22621392, 2012). "Expression of GKN1 is progressively lost from normal mucosa, precancerous to cancerous gastric tissues, while restoration of GKN1 expression induces gastric cancer cells to undergo apoptosis, and enhances sensitivity of gastric cancer cells to 5-FU-induced apoptosis." (PMID 22621392, 2012). "Moreover, restoration of GKN1 expression suppressed gastric cancer cell viability and induced the cells to undergo apoptosis." (PMID 22621392, 2012). "In addition, this study demonstrated that GKN1 was able to increase the sensitivity of gastric cancer cells to 5-FU treatment." (PMID 22621392, 2012). "Gene transfection was used to restore GKN1 expression in gastric cancer AGS cells." (PMID 22621392, 2012). "In addition, several studies observed that GKN1 expression was down regulation in gastric atrophy and intestinal metaplastic lesions and even absence in gastric cancer." (PMID 22621392, 2012). "In this regard, GKN1 could induce cell apoptosis, thus GKN1 could enhance 5-FU antitumor activity in gastric cancer cells." (PMID 22621392, 2012). "Next, we determined whether restoration of GKN1 expression would suppress gastric cancer AGS cells viability." (PMID 22621392, 2012). "Our current study, for the first time, demonstrated the progressive loss of GKN1 mRNA and protein from normal to precancerous and cancer tissue specimens, indicating the role of GKN1 in gastric cancer homeostasis and alteration of GKN1 expression in gastric cancer." (PMID 22621392, 2012). "Previous studies showed decreased GKN1 expression in gastric cancer." (PMID 22621392, 2012). "Previously generated mRNA expression profiles of gastric carcinoma were compared with those of normal gastric antrum and led to the identification of the gastrokine-1 transcript, which accounted for around 1% of the total mRNA in normal stomach but was absent from gastric cancers." (PMID 19057650, 2008). "Thus, CagA facilitated the progression of gastric cancer partially by reducing GKN1 expression." (PMID 35280689, 2022). "This suggests that loss of GKN1 alone is not sufficient to result in increased gastric cancer." (PMID 33947892, 2021). "Interestingly, the serum concentrations of GKN1 protein were significantly more reduced in patients with gastric cancer than in normal healthy individuals and clearly distinguished the patients, with an AUC value of 0.98, which represents a perfect value for clinical application." (PMID 31376239, 2019). "In conclusion, utilizing several specimens from patients with gastric carcinoma, we found that GKN1 expression is significantly reduced in dysplasia and tumor gastric mucosa, and is inversely correlated with the recruitment of H3K9triMe and Suv39H1 to the GKN1 promoter." (PMID 28129645, 2017). "However, it remains to be determined how GKN1 is able to induce apoptosis in gastric cancer cells." (PMID 22621392, 2012). "We found that the GKN1 protein was abundantly expressed in the upper glandular layer of the top one third superficial epithelium, while expression of GKN1 protein was progressively down regulated from normal gastric mucosa, atrophic gastritis, intestinal metaplasia and dysplasia, to gastric cancer." (PMID 22621392, 2012). "However, the actual role of gastrokine-1 with regards to its known decreased expression in gastric cancer is still unknown." (PMID 19057650, 2008). "Decreased expression of gastrokine-1 and the trefoil factor may thus favour the development of gastric cancer by weakening the actin assembly (stress fibers) and disrupting smooth cell-substratum contacts, or inducing loss of anchoring and thus anoikis, a form of apoptosis." (PMID 19057650, 2008).
gastric cancer (continued). "Another study suggested that downregulated serum levels of exosomal Gastrokine 1 (GKN1) protein may be a valid biomarker for diagnosing gastric cancer (GC)." (PMID 38983854, 2024). "Previous studies have revealed that by downregulating MMP2 expression through the NF‐κB pathway, GKN1 inhibits metastasis in GC cells, suggesting that it may be a potential therapeutic target for gastric cancer." (PMID 39524138, 2024). "The expression of gastrokine 1 (GKN1) was decreased in H. pylori-infected gastric mucosa and gastric cancer." (PMID 35280689, 2022). "Similarly, Gastrokine 1’s inhibition of gastric cancer progression may also be dependent on RhoA." (PMID 32831016, 2020). "The serum concentration of GKN1 in healthy individuals (median: 6.34 ng/μL, interquartile range (IQR): 5.66‐7.54 ng/μL) was significantly higher compared with the levels in gastric cancer patients (median: 3.48 ng/μL, IQR: 2.90‐4.11 ng/μL; P < .0001)." (PMID 31376239, 2019). "The aim of this study was to investigate the expression of GKN1 and GKN2 genes as probable biomarkers for gastric cancer." (PMID 30774821, 2018). "However, the mechanism by which GKN1 is inactivated in gastric cancer remains unknown." (PMID 28129645, 2017). "Similar to GKN1, insulin-like growth factor binding protein-3 (IGFBP-3) is a potent tumor suppressor, which is down-regulated in gastric cancer." (PMID 28350359, 2017). "One study demonstrated that GKN1 induces senescence by activating the Ras/Raf/MEK/ERK pathway and its downstream p16/Rb and p21waf effectors in gastric cancer cells." (PMID 25344918, 2014). "Gastrokine-1 (GKN-1), possessing some mitogenic effects on intestinal epithelial cells (IEC-6), was down-regulated in gastric cancer tissue compared to matched normal gastric mucosa in our study." (PMID 24404153, 2014). "Although at much lower levels than primary stomach tissue, GKN1 and GKN2 were both expressed at measurable levels in AGS gastric carcinoma cell lines, with GKN2 expressed at higher levels than all other GC cell lines, or EBV positive B-cell or NPC cell lines." (PMID 24460791, 2014). "We also show that latent EBV infection further reduces GKN1 and GKN2 expression in AGS gastric carcinoma cells, and that siRNA depletion of EBNA1 partially alleviates this repression." (PMID 24460791, 2014). "To study the potential role of EBV and EBNA1 in the transcriptional control of GKN1 and GKN2, we generated an EBV positive AGS gastric carcinoma cell line." (PMID 24460791, 2014). "Finally, in gastric cancer, UBR5 binds to and ubiquitinates gastrokine 1 (GKN1), a tumor suppressor that regulates cell growth and protects gastric mucosal integrity." (PMID 39857943, 2025). "GKN1 derived from gastric tumor cells, however, did not appear to be used in gastric cancer treatment." (PMID 39524138, 2024). "Compared with the normal samples, the results demonstrated that ATP4B, TFF2, GIF, GKN1, and TFF2 were low expressed in tumor samples, suggesting these targets might act as the TSGs in gastric cancer." (PMID 36428568, 2022). "Using this cutoff value for serum GKN1, 44 (8.8%) of the 500 patients with gastric cancer were negative for gastric cancer diagnosis." (PMID 31376239, 2019). "Interestingly, serum GKN1 concentrations in patients with advanced gastric cancer (AGC; median: 3.11 ng/μL, IQR: 2.72‐3.72 ng/μL) were lower than in patients with early gastric cancer (EGC; median: 4.31 ng/μL, IQR: 3.88‐4.88 ng/μL)." (PMID 31376239, 2019). "Moreover, treatment of tumor cells with recombinant human GKN1 reduced the proliferation of AGS cells compared with human embryonic kidney cells (HEK 293) and non-gastric cancer cells (H1355)." (PMID 28129645, 2017). "As it is expressed in normal gastric tissue but absent in gastric cancer tissues, GKN1 protein is treated as a potential biomarker for gastric cancer." (PMID 25999661, 2015).
gastric cancer (continued). "In the present study, three proteins, ApoAI, A1AT, and GKN-1, were down-regulated in the normal gastric tissues compared to gastric cancer tissues.The relationship of ApoAI and gastric cancer has not been reported." (PMID 24404153, 2014). "In stable cells, GKN1 similarly increased expression of TRF1 and reduced hTERT and c-myc protein expression in a time dependent manner, particularly at the chromatin level of gastric cancer cells." (PMID 25344918, 2014). "Here, to investigate whether GKN1 plays a role in senescence and apoptosis of gastric cancer cells, we stably reconstituted GKN1 into AGS and MKN1 gastric cancer cells." (PMID 25344918, 2014). "Significant downregulation or absence of GKN1 expression in seven gastric cancer cell lines were detected and progressive decrease of GKN1 expression from normal mucosa, precancerous tissue, to cancer tissues was observed." (PMID 22621392, 2012). "To further investigate the possible biological functions of GKN1 in gastric cancer, we successfully cloned and transfected GKN1 into gastric cancer AGS cells that do not express GKN1 protein." (PMID 22621392, 2012). "Next, we immunohistochemically stained GKN1 in the tissue sections of normal gastric mucosae (from healthy volunteers), atrophic gastritis, intestinal metaplasia, dysplasia, and gastric cancer and their corresponding distant non-cancerous mucosae." (PMID 22621392, 2012). "Gastrokine-1 is absent from gastric carcinomas as well as from precursor lesions of intestinal metaplasia." (PMID 19057650, 2008). "Furthermore, there is a lack of research on GKN1‐related exosomes isolated from gastric cancer cell lines." (PMID 39524138, 2024). "Our preliminary results did not confirm GKN1 as a potential biomarker for gastric cancer." (PMID 27452910, 2016). "Therefore, our data suggest that GKN1 may play a negative role in homeostasis of telomere length in gastric cancer cells by regulating the expression of telomere-related proteins." (PMID 25344918, 2014). "Because of the lack of a non-tumoral gastric cell line, we analyzed protein expression in GKN1-transfected and non-transfected GC cells (AGS) and in an additional non-transfected gastric cancer cell line (NCI-N87)." (PMID 28129645, 2017).
gastric tumor (6 papers, 2017 to 2024). "No mutation was detected in gastric tumors and hyper-methylation of the GKN1 promoter was only observed in two tumors, whereas DNA copy number and GKN1 mRNA levels were significantly decreased in all GC samples." (PMID 28129645, 2017). "Gastrokine 1 (GKN1), a tumor suppressor like protein which expression is lost in gastric tumors (including adenoma and cancer), was responsible for decreased SOX9 expression in AGS and MKN-1 cells." (PMID 31057614, 2019). "Due to the important roles of GKN1 and GKN2 genes and their relationship, in the gastric mucosal defense mechanism and their gastric tumor suppressor activity, GKN1 and GKN2 might be reliable biomarkers for detecting GC in early stages." (PMID 30774821, 2018).
lung carcinoma (4 papers, 2015 to 2024). "In our study, GKN1 polymorphism rs4254535 was significantly associated with female and better prognosis in patients with advanced lung cancer." (PMID 38250608, 2024). "Previous studies have found that the GKN1 polymorphism rs4254535 is related to the chemotherapy response of lung cancer patients." (PMID 38250608, 2024). "The research investigated the association between the prognosis and the GKN1 polymorphism rs4254535 by using blood samples from 839 Chinese patients with lung cancer." (PMID 38250608, 2024). "In a study on the effect of GKN1 polymorphism on the efficacy of cisplatin chemotherapy in lung cancer, it has been found that GKN1 polymorphism significantly reduce the chemotherapy response of lung cancer patients." (PMID 38250608, 2024). "We selected seven genes (CRP, GPC5, ACTA2, AGPHD1, SEC14L5, RBMS3, and GKN1) that previously reported link to lung cancer (LC) and genotyped single nucleotide polymorphisms (SNPs) of these genes in a case-control study." (PMID 25999661, 2015). "Cumulatively, our findings provide evidence that polymorphisms in C-reactive protein and Glypican 5 genes are associated with lung cancer risk, and GKN1 determines chemotherapy response in Chinese population." (PMID 25999661, 2015). "To further study whether GKN1 polymorphism rs4254535 is associated with the prognosis of lung cancer, we collected 888 blood samples from patients diagnosed with lung cancer." (PMID 38250608, 2024). "The blood samples were taken before treatment to detect GKN1 polymorphism rs4254535 and a follow-up investigation was conducted to explore the association between GKN1 polymorphism rs4254535 and disease progression and prognosis of patients with various types of lung cancer." (PMID 38250608, 2024). "Lung cancer KRT14+ LCs co-express gastrokine 1 (Gkn1) which enhances their metastatic potential by supressing Akt and inhibiting cell death via anoikis." (PMID 39408880, 2024). "Our study firstly reports that polymorphismin GKN1 is influence cisplatin based chemotherapy response in lung cancer patients." (PMID 25999661, 2015). "The authors observed that rs4254535 polymorphism T > C, an SNP in GKN1, was significantly associated with better prognosis in female, non-smoking, No Family History, and adenocarcinoma patients diagnosed with late-stage (stage III + IV) lung cancer." (PMID 38250608, 2024). "The study showed that GKN1 polymorphism rs4254535 T > C significantly reduced the prognosis of lung cancer patients and was relatively strongly associated with non-smoking, no family history, female, and adenocarcinoma patients." (PMID 38250608, 2024). "In our study, GKN1 polymorphism rs4254535 was found to be significantly associated with lung cancer prognosis, especially in adenocarcinoma and non-smoking patients." (PMID 38250608, 2024). "A high level of GKN1 protein, with which Keratin 14 (K14) - high cancer cells could resist anoikic, plays a vital role in promoting metastasis of lung cancer cells with low K14 expression." (PMID 38250608, 2024). "In stratified analysis, we observed that GKN1 polymorphism rs4254535 was significantly associated with better prognosis in lung cancer patients with no smoking history and those diagnosed with lung adenocarcinoma cancer." (PMID 38250608, 2024). "In addition, there were certain limitations in our study: only the association analysis between the rs4254535 single locus and lung cancer prognosis on the GKN1 gene, which lacked the exploration of genome-wide interactions." (PMID 38250608, 2024).
atrophic gastritis (3 papers, 2012 to 2024). "Besides, serum GKN1 concentrations distinguished patients with EGC from normal individuals and subjects with atrophic gastritis without and with IM from GC patients with AUCs of 1.0000, 1.0000 and 0.9892, respectively." (PMID 35066729, 2023).